CTLA4 (cytotoxic T-lymphocyte associated protein 4)
Diseases named in the same sentence as CTLA4 in open-access papers (continued):
Sharing a sentence is not in itself a finding about the gene and the disease.
melanoma (continued). "Indeed, one human trial has recently reported that concurrent blockade of CTLA-4 and PD-1 was synergistic in generating anti-tumor responses in melanoma patients, while adverse immune-related toxicities were no more prevalent than with monotherapy." (PMID 24353898, 2013). "At present, it is not known the physiological role of CTLA-4 on melanoma cells." (PMID 23634660, 2013). "No ADCC was detected upon interaction with CTLA-4- FO-1 melanoma cell line." (PMID 23634660, 2013). "However, in B16 melanoma model using non-transgenic mice, the anti-CTLA-4 mAb augmented the effects of cancer vaccine." (PMID 23755373, 2013). "The potential of CTLA-4 blockade to mobilize anti-tumor immunity has been recapitulated in clinical trials for human melanoma and other solid tumors, and in 2011 a monoclonal anti-CTLA-4 antibody (Ipilimumab) received FDA approval for the treatment of patients with advanced melanoma." (PMID 24353898, 2013). "Prior studies have shown that agonistic 4-1BB antibodies with or without CTLA-4 blockade can promote the rejection of some murine tumors and ameliorate auto-immune toxicity; however, poorly immunogenic tumors such as B16 melanoma do not respond to antibody therapy alone." (PMID 21559358, 2011). "As we have observed previously for combination blockade of CTLA-4 and PD-1, we find that co-administration with an autologous tumor vaccine expressing Flt3-ligand allows these antibodies to co-operate in rejecting more than 50% of pre-implanted B16-BL6 melanomas." (PMID 21559358, 2011). "CTLA4 blockade using the specific antagonistic monoclonal antibodies ipilimumab (formerly known as MDX010 and BMS734016) and tremelimumab (formerly known as CP-675,206 and ticilimumab) reproducibly induce objective tumor responses in a subset of patients with melanoma." (PMID 18452610, 2008). "It is certainly possible that the 3 melanoma antigens studied may not be relevant for CTLA4 blockade-induced melanoma regressions." (PMID 18452610, 2008). "Importantly, KIT-mutant melanomas may not be uniformly immunologically “cold,” as some patients have shown responses to PD-1 or CTLA-4 blockade." (PMID 41301010, 2025). "Similarly, we observed higher FRC-like scores were associated with significantly improved survival in immune checkpoint inhibitor treated patients with lung cancer (p < 0.01; anti-PD1/PD-L1) and melanoma (p < 0.001; anti-CTLA4/PD-1); unlike HNSCC, iCAF were not prognostic." (PMID 39757146, 2025). "For example, combination PD-1/CTLA-4 blockade may appear to produce more vitiligo, but this may be due to its more frequent use in melanoma, whereas anti-angiogenic agents are not used in melanoma." (PMID 38254829, 2024). "Hence, CTLA-4 humanized monoclonal antibodies (mAB) such as ipilimumab and tremelimumab have demonstrated great clinical benefits in many different malignancies, including melanoma, lung carcinoma, and renal cell carcinoma, but not in BC." (PMID 38956700, 2024). "Also, a comprehensive analysis of biomarkers indicating the likelihood of survival or response to anti-CTLA-4 and anti-PD-1 monotherapy in patients with advanced melanoma revealed a consistent negative correlation between Treg cells and response rates, PFS, and OS in most of the studies." (PMID 39273452, 2024). "Furthermore, a simultaneous combination treatment of anti‐PD‐1 and anti‐CTLA‐4 with STING‐agonist‐containing liposomes effectively reduced the number of pulmonary metastatic nodules in a mouse melanoma lung metastasis model, whereas free cGAMP + anti‐PD‐1 + anti‐CTLA‐4 did not." (PMID 37560754, 2023). "Anti-CTLA-4 monoclonal antibody (tremelimumab and ipilimumab) has been found to block the interaction of CTLA-4 with CD80 and CD86, which may be used in the treatment of impaired cellular immunity in the course of viral infections and neoplastic diseases, e.g., melanoma." (PMID 35158937, 2022).
melanoma (continued). "The seminal observation that blocking the prototypical immune checkpoint receptor cytotoxic T-lymphocyte antigen-4 (CTLA-4) could mediate tumor regression in murine models led to the clinical development and approval of anti-CTLA-4 as a treatment for patients with advanced melanoma." (PMID 35154142, 2022). "Furthermore, functional assays using mice with melanoma that are resistant to anti-CTLA-4 Ab plus radiation therapy revealed that inhibition of tumor IFN-γ signaling decreases ISGs in cancer cells, while it increases the number and IFN-γ production of CD8+ T cells and activates NK cells in melanoma." (PMID 35432377, 2022). "Consequently, inhibitory antibodies were developed, such as ipilimumab, blocking CTLA-4 function and thereby facilitating positive co-stimulation with CD28 and allowing the rescue of exhausted CD8 T cells and NK cells, leading to tumor control of colon and melanoma tumors." (PMID 34572799, 2021). "Preliminary data from a clinical trial of LAG-3 antibody (liratrimab) in combination with nivolumab in melanoma patients suggested that it was more effective than nivolumab alone, suggesting that the anti-LAG-3 antibody may have clinical efficacy as a third ICI pathway following PD-1 and CTLA-4." (PMID 34685400, 2021). "However, approximately 40–65% of melanoma patients have no response to or develop relapse after anti-PD-1 therapy due to primary or acquired resistance, and over 70% of patients experience anti-CTLA-4 treatment failure." (PMID 34025664, 2021). "Immunotherapies, such as anti-CTLA-4 or anti-PD-1/anti-PD-L1 antibodies, have better response rates and improvement in patient survival with advanced melanoma, but clinical trial data suggest that not all melanoma patients are responsive to single agent monoclonal antibodies for CTLA-4/PD-1/PD-L1." (PMID 33256089, 2020). "In addition, studies have also shown that the overall response rate of melanoma patients treated with a combination of the oncolytic virus Imlygic (T-VEC) and the checkpoint inhibitor CTLA-4 antibody, has doubled compared with a single treatment with Yervoy (Ipilimumab) CTLA-4 antibody." (PMID 32269962, 2020). "This phenomenon has been observed in pre-clinical models of non-small cell lung cancer, melanoma, and pancreatic cancer, as well as an autologous humanized mouse model of renal cell carcinoma in response to anti-PD-1 antibody therapy but not anti-CTLA-4 antibody therapy or chemotherapy." (PMID 30400822, 2018). "However, our study had not a sufficient statistical power to conclude that the lack of benefit from anti-CTLA-4 in females, in the overall population, was due to the presence in the analysis of tumor types different from melanoma that do not respond to this therapy." (PMID 30545122, 2018). "In melanoma, anti-PD-1 antibody combinations (either pembrolizumab or nivolumab) showed rates of overall response and disease control similar to those produced by the approved combination of anti-PD-1 and anti-CTLA-4 antibodies (ipilimumab) without the significant side effects of the latter." (PMID 30068361, 2018). "Indeed, the frequent use of systemic corticosteroids to treat toxicities may explain why combination therapy targeting CTLA-4 and PD-1 has a higher overall response rate in melanoma but does not appear to induce a substantial improvement in overall survival." (PMID 29230210, 2017). "Interestingly, when a stimulatory ICOS antibody was used in combination with anti-CTLA-4, there was a significant improvement in tumor rejection in both melanoma and colon cancer mouse models, suggesting that HPV(+) tumors expressing high levels of ICOSLG may respond better to anti-CTLA-4 therapy." (PMID 27462861, 2016). "Thus, a fully humanized anti-CTLA-4 monoclonal antibody immunoglobulin (Ig) G1 isotype (ipilimumab) was approved by the Food and Drug Administration (FDA) in 2011 at a dosage of 3 mg/kg every 3 weeks for four cycles in advanced melanoma, with evidence of improved survival." (PMID 26337719, 2015).
melanoma (continued). "The main advantage of the NPS approach is its identification of any significant heterogeneity that might be captured in the data from the clinical, or in this case the CTLA-4 based immune regulation mechanism that we focused upon in this study of subjects with and without melanoma." (PMID 24475110, 2014). "Combinatorial treatment with anti-CD25 and anti-CTLA-4 could be applied to the E6-RHDV-VLP-PADRE vaccination regimen, particularly as a good therapeutic outcome with the antibodies used in combination has been shown in models of mouse melanoma, colon carcinoma and previously in the TC-1 HPV model." (PMID 23799135, 2013). "In melanoma, anti-CD47 alone does not induce lasting antitumor immune responses in B16 tumors unless combined with anti-PD-L1, but not anti-CTLA4." (PMID 38414061, 2024). "In this study, we found immature TLSs in anti-CTLA4 resistant tumors, however no TLS was identified in anti-PD1 resistant melanoma." (PMID 38594286, 2024). "In contrast, MCM from 2 out of three primary melanoma cell lines tested (WM115 and WM35) did not inhibit the expression of CTLA4 in PBMCs." (PMID 37197667, 2023). "Some examples of these include termination of a basket trial for anti-CTLA-4 and PD-L1 combination therapy assessment in metastatic solid tumors (NCT03982173) and anti-CTLA-4 in advanced melanoma (NCT 01740401) due to non-encouraging results." (PMID 37445336, 2023). "In contrast to results of our murine melanoma model, domatinostat (a class I HDAC inhibitor) does not add benefit to neoadjuvant anti-PD-1 ± anti-CTLA-4 in patients." (PMID 36920329, 2023). "The reliable TIDE signatures were computed in five cancer types without lung cancer, and only melanoma has publicly available data on tumor expression and clinical outcome of patients treated with anti-PD1 or anti-CTLA4." (PMID 36437954, 2022). "In 2019, a phase Ib/II clinical trial was completed combining anti-CTLA4 and anti–PD-1 with RTA-408 in melanoma patients, but results have not been formally posted (NCT02259231)." (PMID 35040434, 2022). "However, this difference may reflect tumor type heterogeneity rather than differential drug effects, because all anti-CTLA-4 therapies were performed in melanoma and anti-PD-1/anti-PD-L1 therapies were mainly adopted in other tumor types in HER2-mutated patients." (PMID 35281032, 2022). "Patients in both studies were treated with ICI therapy (with anti-PD-1 or anti-CTLA4) and were divided as responders (17 melanoma and 6 BCC) and non-responders (31 melanoma and 5 BCC) according to RECIST criteria." (PMID 35634306, 2022). "In Braf/Pten melanoma-draining LNs, TSLP promoted not only GATA3+ Th2 cells, but also GATA3+ Tregs expressing a specific signature including ST2, CCR8, ICOS, PD-1, CTLA-4, OX40, and IL-10 — but not Th2 cytokines IL-4 and IL-13." (PMID 36107619, 2022). "Ipilimumab, which targets CTLA-4, is the first-in-class FDA-approved ICI for the treatment of melanoma that does not respond to chemotherapy." (PMID 36159809, 2022). "We separated a cohort of patients into 2 groups: (a) patients with melanoma responding to anti–CTLA-4 (per RECISTv1.1) (n = 6); and (b) nonresponding to anti–CTLA-4 (n = 8)." (PMID 35552271, 2022). "The efficacy of anti-CTLA4 monotherapy versus combined anti-CTLA-4 and anti-PD-1 therapy has not been well defined in melanoma patients who progressed on anti-PD-1 monotherapy." (PMID 33435389, 2021). "Two independent groups presented cases where concurrent CTLA-4 ICB and RT resulted in regression at both the targeted and non-targeted melanoma lesions, demonstrating an abscopal effect." (PMID 33218169, 2020). "CT26 was highly responsive to CTLA4 checkpoint inhibitors, but not to PD-1 inhibitors, while other models including the B16F10 melanoma model did not respond significantly to either of the checkpoint inhibitors." (PMID 31898484, 2020).
melanoma (continued). "This is of particular interest, since anti-CTLA4/ipilimumab was shown to engage non-classical monocytes ex vivo, resulting in antibody-dependent cell-mediated cytotoxicity (ADCC) of Tregs in melanoma patients." (PMID 32507967, 2020). "Thus, IL-10 blockade in the metastatic melanoma environment may normalize DC development and allow for development and/or attraction of inflammatory non-classical monocytes, effectively facilitating immune checkpoint blockade by anti-PD1 and anti-CTLA4/ipilimumab, respectively." (PMID 32507967, 2020). "Compared with B16-Ova, the non-immunogenic B16-F10 melanoma was significantly less responsive to monotherapy treatments; however, TLR9 agonist (p = 0.0054), anti-CTLA-4 (p = 0.0125) and anti-PD-1 (p = 0.0283) all showed a modest capacity to extend survival." (PMID 31771649, 2019). "This is consistent with data in immunogenic melanoma models, where administration of FTY720 to mice with established tumors did not influence the outcome of anti-CTLA4 and anti-PD1 immunotherapy." (PMID 29725089, 2018). "In melanoma, tumor tissue PD-L1 expression showed significant correlation with response in five out of eight PD-1 ICI studies but did not predict response to CTLA-4 ICI therapy." (PMID 29970158, 2018). "Despite the impressive impact of CTLA4- and PD1:PDL1-targeted cancer immunotherapy, a significant proportion of patients, including those with melanoma, failed to respond." (PMID 29371600, 2018). "CTLA4 and PD1 are considered to be non-redundant pathways, and this combination has been tested in melanoma patients confirming the synergism of blockade of these two IRs [27•]." (PMID 29502288, 2018). "The IPS profile differs between melanoma patients who respond or do not respond to immune checkpoint blockade (ICB) therapy (for anti-PD-1 and anti-CTLA-4), posing clear potential implications of this algorithm as a response predictor tool to immunotherapy." (PMID 30133560, 2018). "Yervoy, the first anti-CTLA-4 antibody, can deplete regulatory T cells by engaging ex vivo Fc gamma receptor IIIA-expressing, non-classical monocytes in melanoma patients." (PMID 32793247, 2018). "Similar observations with no DLTs have been reported in a Phase 1 study of 18 melanoma patients receiving combination therapy with T-VEC and anti-CTLA-4 antibody." (PMID 28796812, 2017). "Infiltration of human melanoma tumors by CD8+ T cells, which co-express PD-1 and CTLA-4 at high levels and produce IFN-γ efficiently but not TNF, has been proposed as a good predictive marker of anti-PD-1 therapy." (PMID 29273790, 2017). "We further confirmed the expression of CTLA-4 and reactivity of Ipilimumab by performing qRT-PCR in a CTLA-4+ melanoma tissue sample consisting of almost, if not all, melanoma cells." (PMID 23634660, 2013). "In models using poorly immunogenic tumors (e.g., B16 melanoma), anti-CTLA-4 alone does not control tumor growth, but in conjunction with GM-CSF tumor cell vaccine, anti-CTLA-4 synergizes to eradicate established B16 melanoma." (PMID 21281484, 2011). "Our results suggest that high plasma CD27s levels predict poorer efficacy of anti-PD1 monotherapy in melanoma but not for the combination therapy, supporting the need for therapeutic escalation with the anti-PD1 and anti-CTLA4 combination or other combination (anti-Lag3)." (PMID 40148586, 2025). "Notably, anti-CTLA-4 drugs have not been shown to improve ORR in GTM, unlike their efficacy in melanomas of the naso-oral mucosa." (PMID 40303398, 2025). "A retrospective analysis of patients with melanoma and CRC who did not respond to anti-CTLA-4 or anti-PD-1 therapy revealed these patients had tumors with gene mutations, including JAK1/2 and IFN-γ receptor 1/2 (IFNγR1/2), which are critical for IFN-γ signaling." (PMID 40075727, 2025). "Anti-CTLA-4 antibody, although not effective by itself against larger tumors, can restore the anti-tumor efficacy of CpG + OX40 in larger A20 lymphomas but not in larger B78 melanomas." (PMID 37016127, 2023).
melanoma (continued). "Furthermore, by re-analysis of the public monocytic melanoma dataset GSE120575, we found that patients who did not respond to PD-1/CTLA4 inhibitors had higher SIRPα expression on monocyte/macrophage cells." (PMID 37291116, 2023). "Here, we identify that melanomas defective of IFN-γ signaling are not only resistant to IFN-γ-induced cell death but also have reduced infiltration of CD8+ T cells and lack of anti-CTLA-4 induced functional rejuvenation of TILs, posing a dual resistance to ICBs." (PMID 36008408, 2022). "This study confirmed previously observed data from melanoma biopsies of patients treated with anti-CTLA-4 followed by PD-1 blockade, namely that a more clonal baseline TCR repertoire was predictive of response to PD-1, but not to CTLA-4 blockade." (PMID 36550555, 2022). "Purified IgG from melanoma patients with or without grade III-IV toxicity, as well as healthy subjects as control, were injected into humanized FcγR mice treated with anti-PD-1, anti-CTLA-4 or both anti-PD-1 and anti-CTLA-4." (PMID 36058945, 2022). "ICOS, a T-cell costimulatory molecule of the CTLA-4/PD-1/CD28 family, plays a nonoverlapping function with CD28 and is highly expressed by TA-Tregs in breast carcinoma, ovarian carcinoma, follicular lymphoma, melanoma, RCC and gastric cancer." (PMID 33924428, 2021). "Variable levels of CTLA-4 expression were detected in circulating and tumor-infiltrating NK cells and non-NK cell ILC in melanoma, hepatocellular carcinoma, breast and gastrointestinal cancers, with higher levels found in tumor-infiltrating ILC compared to circulating cells." (PMID 34885076, 2021). "Anticancer strategies targeting CTLA-4, PD-1, PD-L1 demonstrated clinical efficacy in many cancer types leading to several FDA-approved antibodies for treating melanoma, lung carcinoma (mainly, non-squamous non-small-cell lung carcinoma, NSCLC) and DNA-mismatch repair-deficient cancers." (PMID 33466674, 2021). "Moreover, in melanoma patients, a higher infiltration by CD68+CD16+ classically activated (M1) macrophages was found in tumors of responders to CTLA-4 as compared to non-responders." (PMID 32457745, 2020). "Interestingly, in a murine preclinical model of melanoma where anti-CTLA4 treatment alone was not efficient, a combination of IL2 superagonist and anti-CTLA4 led to reduced tumor growth and this effect was abolished when NK cells were depleted." (PMID 31614774, 2019). "Antibodies which activate the T-cell co-stimulatory receptor 4-1BB or block the co-inhibitory receptor CTLA-4, have demonstrated broad anti-tumor effects but cannot induce rejection of the poorly immunogenic B16-BL6 melanoma without the aid of additional therapeutic interventions." (PMID 21559358, 2011). "For OVA-expressing melanoma, CTLA-4 blockade or Treg depletion (with anti-CD25 mAb) showed improvement in tumor control and enhanced induction of OVA-specific CD8+ T cells whereas CTLA-4 mAb application without RF ablation did not mediate the same effects." (PMID 22242035, 2011). "While several HDAC inhibitors have been tested in combination with ICIs, such as anti-PD-1 and anti-CTLA4 therapy against multiple advanced-stage solid tumors, to the best of our knowledge, the effects of HDAC4 inhibitors with ICIs have not been reported, particularly in melanoma patients." (PMID 40361444, 2025). "The phase I/II IGNYTE study (NCT03767348) evaluated RP-1 in 156 patients with advanced melanoma who had at least one measurable and injectable tumor (≥1 cm) and had experienced disease progression after receiving anti-PD1 monotherapy, with or without anti-CTLA4 therapy, for a minimum of eight weeks." (PMID 40733704, 2025). "Although the response rates to ICIs in patients with melanoma is improving, around half of melanoma patients still do not respond combination anti-PD-1/anti-CTLA-4 therapies, whilst single agent response rates are even lower at ~ 30–40% for anti-PD-1 agents and ~ 10–15% for anti-CTLA-4 agents." (PMID 38533720, 2024).